LDHA (lactate dehydrogenase A)
Diseases named in the same sentence as LDHA in open-access papers (continued):
Sharing a sentence is not in itself a finding about the gene and the disease.
breast cancer (continued). "It has previously been reported that the expression and activity of LDHA were increased in taxol-resistant MDA-MB-435 breast cancer cell lines and that the down-regulation of LDHA significantly increased sensitivity to taxol." (PMID 25973606, 2015). "The impact of HSF1 on glucose metabolism was also confirmed by the finding that HSF1 directly activates the LDHA gene, which supports “addiction to sugar” in human breast cancer cells." (PMID 24467529, 2014). "Expression of LDH depends on HSF1, which binds to the LDHA gene promoter in human breast cancer cells overexpressing ERBB2." (PMID 24467529, 2014). "Consistent with selective inhibition of LDHA, the most sensitive breast cancer cell lines to lactate inhibition in hypoxic conditions were cells with low expression of LDHB." (PMID 24280423, 2013). "In contrast, it has been found that ERRα activates the LDHA gene promoter through ERRE in HepG2 human liver cells or MCF7 human breast cancer cells." (PMID 23516535, 2013). "Breast cancer malignancy can be categorized by the level of LDHA expression." (PMID 40295451, 2025). "KCNK1 is bound to and activates lactate dehydrogenase A (LDHA), which enhances histone lysine lactylation to induce the expression of several downstream genes as well as LDHA itself; this increases glycolysis and lactate generation in breast cancer cells." (PMID 40295451, 2025). "Furthermore, Dio3os interacts with polypyrimidine tract binding protein 1 (PTBP1) to facilitate a metabolic shift towards glycolysis in breast cancer cells, thereby promoting increased expression of lactate dehydrogenase A (LDHA)." (PMID 41235096, 2025). "Notably, siRNA-mediated knockdown of LDHA further sensitized breast cancer cells to DOX, highlighting the pivotal role of glycolytic suppression in enhancing chemosensitivity." (PMID 40861817, 2025). "Notably, elevated LDHA expression acts as a vicious positive feedback loop to decrease tumor cell adhesion and stiffness, ultimately leading to breast cancer spread, invasion, and proliferation." (PMID 40295451, 2025). "In breast cancer, Potassium Two Pore Domain Channel Subfamily K Member 1 has been confirmed to promote tumor cell proliferation and metastasis and accelerate breast cancer progression by activating LDHA and up-regulating H3K18 lactation." (PMID 41041328, 2025). "In summary, evidence suggests that GLUT1, HK2, LDHA, MCT1, PKM2 and PFK1 could become potential biomarkers, either diagnostic or prognostic, in breast cancer, depending on the molecular subtypes and treatment involved." (PMID 41154605, 2025). "In breast cancer, elevated LDHA levels have been detected in cancer tissue and patient serum, suggesting that LDHA could be released from breast cancer cells into the body circulation and remain stable for clinical detection." (PMID 41154605, 2025). "LDHA has been shown to improve survival in tamoxifen‐resistant breast carcinoma cells." (PMID 40956032, 2025). "Consequently, inhibiting LDHA by pharmacological and genetic means sensitizes these breast carcinoma cells to tamoxifen." (PMID 40956032, 2025). "Interestingly, overexpression of LDHA elevated the intracellular pan histone lactylation and H3K18la modification in breast cancer." (PMID 38905316, 2024). "Indeed, inhibition of lactate production through targeting LDHA has shown significant benefits in multiple cancers, including melanoma, lung cancer, breast cancer, cervical cancer, leukemia, glioma, and adrenal cancer." (PMID 37791390, 2024). "In addition, results of qRT-PCR and western blotting demonstrated that overexpression of LDHA rescued the expression of downstream targets reduced by knockdown of KCNK1 in breast cancer cells." (PMID 38905316, 2024).
breast cancer (continued). "Furthermore, STAT3 regulates aerobic glycolysis by stimulating hexokinase 2 in breast cancer, and upregulating lactate dehydrogenase A (LDHA) in myeloma." (PMID 38245798, 2024). "KCNK1 binds to and activates LDHA, promotes lactate production, and catalyzes H3K18la modification of target genes in breast cancer cells, and also raises the level of histone lactylation modification of LDHA itself, which further sustained LDHA expression in a positive feedback loop." (PMID 38905316, 2024). "Due to its ability to inhibit LDHA, vitamin C may be considered an effective therapy for stress-related breast cancer." (PMID 39678492, 2024). "In immunodeficient mouse model with breast cancer, chronic stress-induced epinephrine activates key enzyme LDHA to produce lactic acid, forming an acidic microenvironment to facilitate USP28-mediated deubiquitination of MYC, resulting in enhanced cancer stemness." (PMID 39054537, 2024). "Further studies unexpectedly revealed that KCNK1 increased the glycolysis and lactate production in breast cancer cells by binding to and activating lactate dehydrogenase A (LDHA), which promoted histones lysine lactylation to induce the expression of a series of downstream genes and LDHA itself." (PMID 38905316, 2024). "In addition, MTT and colony formation assays revealed that overexpression of LDHA rescued the inhibitory effect of KCNK1 knockdown on the proliferation of breast cancer cells." (PMID 38905316, 2024). "Our data further demonstrated that KCNK1 induced the metabolic reprogramming of breast cancer cells via LDHA, which accelerated lactate production, catalyzed lactylation modifications of a series of downstream target genes, and thus promoted the malignant progression of breast cancer." (PMID 38905316, 2024). "Furthermore, hexokinase (HK) and lactate dehydrogenase-A (LDHA), two essential glycolysis-related enzymes, are strongly active in breast cancer and linked to the development and spread of the disease." (PMID 39791706, 2024). "LDHA is crucial for sustaining breast cancer stemness and triggering metastasis." (PMID 39394200, 2024). "We found that while LDHA levels are slightly higher in activated lymphocytes compared with other normal tissues, LDHA levels in glycolytic malignant tissues, such as melanoma, colorectal cancer, breast cancer, and B cell lymphoma, are significantly higher." (PMID 39225102, 2024). "Importantly, activated LDHA serves as a positive feedback, thereby sustaining the malignant progression of breast cancer." (PMID 38905316, 2024). "Growth suppression of breast cancer cells by MiR-30a-5p has also been attributed to dampening of aerobic glycolysis by inhibition of lactate dehydrogenase A and expression of this enzyme correlated negatively with expression of miR-30a-5p for breast cancer patients." (PMID 37569466, 2023). "We further examined the role of LDHA in TMEM105-mediated metastasis of breast cancer cells." (PMID 36737428, 2023). "Moreover, LDHA has been reported to promote glycolysis and autophagy in ER-positive, tamoxifen-resistant human breast cancer cells, and LDHA knockdown or inhibition (by oxamate treatment) in these cells restored the sensitivity to tamoxifen." (PMID 37444501, 2023). "In addition, a recent study revealed that epinephrine, induced by chronic stress, promotes breast cancer stem-like traits through LDHA-dependent metabolic rewiring." (PMID 37444501, 2023). "It has been shown that the expression of LDHA is notably elevated in breast cancer." (PMID 36737428, 2023). "As shown by our work, targeting tyrosine phosphorylation of LDHA by SPRY2 might be prospective in stroma of breast cancer." (PMID 37507768, 2023). "Moreover, depletion of LDHA in mouse mammary tumors enhanced the therapeutic activity of the CTLA-4 blockade." (PMID 37444501, 2023). "SPRY2 has been reported to interact with SRC and SRC could phosphorylate LDHA at tyrosine 10 in breast cancer." (PMID 37507768, 2023).
breast cancer (continued). "YY1 overexpression could reverse the decrease of glucose uptake, lactate production, ATP release, HK2, and LDHA proteins in circYY1 depletion breast cancer cells." (PMID 37060064, 2023). "Additionally, quantitative analysis of LDHA expression in breast cancer samples showed that LDHA expression was positively related to TMEM105 expression, particularly in BCLM tissues." (PMID 36737428, 2023). "With the advances in research, LDHA has emerged as a biomarker and therapeutic target for cancer, suggesting that targeting LDHA may be a reliable way to treat breast cancer." (PMID 37204526, 2023). "For example, it has been shown to reduce LDHA expression in a breast cancer cell line." (PMID 37915411, 2023). "Additionally, they demonstrated that the MORC2–c-Myc–LDHA signaling axis contributes to the migration of breast cancer cells." (PMID 37892209, 2023). "The aberrant activation of LDHA by TMEM105 might be the result of the metabolic adaptation for the survival of breast cancer cells in the cancer microenvironment." (PMID 36737428, 2023). "There are a number of studies indicating that LDHA expression is elevated in a wide variety of cancers, including colorectal cancer, breast cancer, pancreatic cancer, and oral squamous cell carcinoma, and that its level is closely correlated with tumor progression." (PMID 36555705, 2022). "It has also been documented that the promoters of pyruvate kinase (PK) and lactate dehydrogenase (LDHA) genes, key enzymes in the glycolytic process, are highly methylated in breast cancer-associated CAFs, which increases pyruvate kinase M2 (PKM2) and LDHA expression." (PMID 36046791, 2022). "In consistence with the result of cell lines, AI-resistant breast cancer samples featured a generally higher expression of LDHA-203 (with 3’UTR) than AI-sensitive groups, while the latter ones exhibited more upregulated expression of LDHA-220 (with unique 5’UTR)." (PMID 36418319, 2022). "In addition, galloflavin has been reported to bind to free LDHA and inhibit glycolysis in breast cancer cells, which inhibits cancer growth." (PMID 36230492, 2022). "Targeting LDHA through miR-30a-5p could be a potential therapeutic strategy in breast cancer for its obvious effect in suppressing breast cancer metastasis." (PMID 36407005, 2022). "And its precursor, (-)-epigallocatechin, as an LDHA inhibitor could significantly inhibit breast cancer growth and induce apoptosis." (PMID 36247675, 2022). "To further strengthen the pathological correlation between Zeb1 expression and aerobic glycolysis in human breast cancer, we performed immunohistochemical staining for Zeb1, LDHA and MCT4 (a lactate transporter marker) in 128 samples of primary breast carcinoma." (PMID 35246504, 2022). "Also in breast cancer, miR-30a-5p acts through the inhibition of LDHA expression, leading to a decreased glucose uptake, lactate production, ATP generation, and ECAR as well as an increased OCR." (PMID 35348905, 2022). "In various cancers, including breast cancer, nasopharyngeal cancer, gallbladder cancer, and PC, LDHA can promote malignant progression by increasing the production of lactic acid, accelerating the uptake of glucose, and regulating many cancer-related molecules." (PMID 35193567, 2022). "In addition, lncRNA SNHG7, a transcriptional target of MYC, positively regulated LDHA level in glycolysis in breast cancer as well." (PMID 36033372, 2022). "Previous studies have proposed that miR-28-5p and LDHA may be involved in breast cancer development." (PMID 36109751, 2022). "Moreover, in breast cancer patients, miR-30a-5p negatively correlates with LDHA expression and increases FDG uptake." (PMID 35348905, 2022). "LDHA had a high level of expression in the claudin-low breast cancer tissue." (PMID 36685583, 2022).
breast cancer (continued). "Suppression of LDHA expression in breast cancer cells induced cellular ROS accumulation with alteration of mitochondrial function, morphology, and metabolisms, thus resembling the pathological mitochondrial clearance observed in the breast muscle of chickens affected with severe WB abnormality." (PMID 36190974, 2022). "This led us to hypothesize that vitamin D treatment alone and/or in combination with LDHA inhibitors might be a therapeutic strategy in breast cancer, acting on both cancer and stromal cells to potentiate the chemotherapeutic response in breast tumors." (PMID 33714987, 2021). "In patients, POU1F1 and LDHA mRNA expression was correlated with breast cancer clinical outcome." (PMID 33714987, 2021). "Furthermore, the co-expression analysis showed that LDHA was negatively correlated with the expression of ALDH1A1 but positively correlated with the expression of CD44 in human breast cancer samples based on the TCGA data set." (PMID 34178639, 2021). "Chronic stress-induced up-regulation of epinephrine could activate lactate dehydrogenase A (LDHA) to generate lactate and promote breast cancer stem-like properties in a rodent model." (PMID 34869378, 2021). "Taxol-resistant breast cancer cells show an increased expression of lactate dehydrogenase-A (LDH-A), an enzyme in glycolysis, and targeting LDH-A could re-sensitize these cells to Taxol." (PMID 33918653, 2021). "Furthermore, pharmacological and genetic LDHA blockade reduces cell migration and invasion and, interestingly, decreases breast cancer cell proliferation under hypoxic environment." (PMID 33714987, 2021). "LDHA inhibition results in increased mitochondrial pathway apoptosis via ROS production and elevated levels of Bax, cleaved poly (adenosine diphosphate-ribose) polymerase, cleaved caspase-9, cytoplasmic cytochrome C, and superoxide anion in breast cancer." (PMID 34540667, 2021). "MiR-30a-5p could inhibit growth and metastasis by inhibiting the LDHA-mediated Warburg effect in breast cancer." (PMID 35127693, 2021). "Finally, to study the possible relationship between POU1F1/LDHA expression and clinical outcome, POU1F1 and LDHA mRNA was analyzed in a dataset of human breast cancer patients." (PMID 33714987, 2021). "This hypothesis needs to be further fully investigated and targeting LDHA combined with CCL2/CCR2 antagonists may provide a better therapeutic outcome for breast cancer." (PMID 34178639, 2021). "Phosphorylated LDHA could promote head and neck cancer and breast cancer cells invasion and metastasis." (PMID 33403045, 2021). "Taken together, LDHA mediates a vicious cycle of mutual promotion between BCSCs plasticity and TAMs infiltration, which may provide an effective treatment strategy by targeting LDHA for breast cancer patients." (PMID 34178639, 2021). "c-Myc through the lncRNA-SNHG7/miR34a-5p/LDHA axis could regulate glycolysis in breast cancer cells." (PMID 33123468, 2020). "To this end, we examined lactate concentration, LDH activity, and isozyme profile, as well as protein expression and tissue localization of LDHA and LDHB in paired biopsies of malignant tumor tissue and tumor-associated adipose tissue from normal-weight and overweight/obese women with breast cancer." (PMID 33353120, 2020). "Finally, in paclitaxel-resistant breast cancer cells, synergistic effects on inducing apoptosis were shown in LDHA downregulated cells or with oxamate (a pyruvate analog that inhibits the conversion of pyruvate to lactate) association." (PMID 32211323, 2020). "LDHA expression and activity are higher in taxol-resistant breast cancer cells." (PMID 32211323, 2020). "Moreover, some critical glycolysis-related enzymes, such as hexokinase (HK) and lactate dehydrogenase-A (LDHA), are highly activated in breast cancer and related to cancer growth and progression." (PMID 33489906, 2020).
breast cancer (continued). "Indeed, LDHA was predominantly localized in breast cancer cells, in contrast to benign tumors where LDHB was predominantly localized in breast epithelium." (PMID 33353120, 2020). "In head and neck and in breast cancer cells, Src phosphorylates and enhances LDHA." (PMID 32673341, 2020). "Several studies have reported that LDHA is highly expressed in various cancers such as pancreatic cancer, gastric, gallbladder, and breast cancers, as well as nasopharyngeal and hepatocellular carcinomas; its expression is positively correlated with the malignant progression of the cancers." (PMID 31921691, 2019). "High level of LDHA expression was observed in pancreatic cancer and breast cancer, suggesting that it might be a promising therapeutic target and prognostic biomarker." (PMID 31989041, 2019). "Finally, in paclitaxel-resistant breast cancer cells, synergistic effects on promoting apoptosis were observed when LDHA was genetically downregulated or when paclitaxel was combined with oxamate." (PMID 30456204, 2018). "Moreover, breast cancer cells with acquired resistance to taxol were re-sensitized to this chemotherapeutic by inhibiting LDHA." (PMID 29541451, 2018). "Other studies have confirmed that miR-34a targets LDHA in colorectal cancer and breast cancer." (PMID 28915924, 2017). "Simultaneously targeting PDL1 and LDHA, which would combine immunotherapy and metabolically targeted treatments, might shed some light on the treatment of breast cancer, especially TNBC." (PMID 28915924, 2017). "Moreover, previous studies of colorectal cancer, breast cancer and non-small cell-lung cancer have demonstrated that LDHA expression and activity are elevated in neoplasms." (PMID 28874393, 2017). "Further studies confirmed that miR-34a targets LDHA in colorectal cancer and breast cancer." (PMID 28915924, 2017). "MiR-34a targets LDHA in breast cancer, colon cancer, cervical cancer, and liver cancer." (PMID 28894025, 2017). "Indeed, IHC staining revealed that the 14-3-3ζ protein levels were significantly correlated with the LDHA protein levels in these breast cancer specimens." (PMID 27150057, 2016). "Together, our data demonstrate that overexpression of 14-3-3ζ in early stage pre-cancerous breast epithelial cells may trigger an elevated glycolysis and transcriptionally up-regulating LDHA, thereby contributes to human breast cancer initiation." (PMID 27150057, 2016). "It suggests that 14-3-3ζ-induced LDHA upregulation is critical for hMEC early transformation and breast cancer early initiation but may be less critical as cancer progresses and adapts to a more complex metabolic environment." (PMID 27150057, 2016). "In summary, our studies defined a novel role of 14-3-3ζ during early transformation and early-stage breast cancer by transcriptionally upregulating LDHA and functionally increasing glycolysis, which ultimately facilitate breast cancer initiation and progression." (PMID 27150057, 2016). "Our findings provide significant insights into the function of LDHA in breast cancer, and targeting LDHA through miR-34a may be a novel, targeted therapeutic strategy for breast cancer." (PMID 26902416, 2016). "It has been reported that LDHA has a significant role in Taxol-resistant breast cancer cells." (PMID 25789051, 2015). "It has been reported that the inhibition of LDHA could reverse taxol resistance in breast cancer cells, which implies the role of glycolytic enzymes and the Warburg effect in chemoresistance." (PMID 26158266, 2015). "A study has also shown that LDHA is important in Taxol resistant breast cancer cells." (PMID 25789051, 2015). "Furthermore, in breast cancer cells, the downregulation of MIDN suppressed the colony formation abilities and lessened cell-cycle-associated and stemness-associated genes; in gastric cancer, the knockdown of MIDN diminished the mRNA levels of Nanog and LDHA." (PMID 40002690, 2025).